RNU1-28P (RNA, U1 small nuclear 28, pseudogene)
Synonyms: RNU1-8; RNU1-8P
Gene: Small nuclear RNA gene on chromosome 14 (34,556,226 to 34,556,389, reverse strand). Ensembl gene ENSG00000206588.
Homologues: Orthologues: chimpanzee U1 (100% identical), dog U1 (100% identical), guinea pig U1 (100% identical), pig U1 (100% identical). Paralogues in human: RNU1-1 (100% identical), RNU1-2 (100% identical), RNU1-27P (100% identical), RNU1-3 (100% identical), RNU1-4 (100% identical), RNVU1-18 (100% identical), RNVU1-29 (100% identical), U1 (100% identical), RNVU1-28 (99% identical), RNVU1-7 (99% identical), RNVU1-31 (99% identical), RNU1-89P (97% identical), and 134 more.